U3 (Small nucleolar RNA U3 )
Synonyms: LOC124906196
Gene: Small nucleolar RNA gene on chromosome 2 (240,289,216 to 240,289,443, forward strand). Ensembl gene ENSG00000276366.
Gene Ontology:
Biological process: RNA processing
Cellular component: nucleolus
Homologues: Orthologues: chimpanzee U3 (77% identical), macaque U3 (74% identical), pig U3 (59% identical). Paralogues in human: U3 (70% identical), SNORD3P1 (69% identical), U3 (68% identical), SNORD3G (66% identical), U3 (65% identical), SNORD3E (64% identical), U3 (64% identical), SNORD3D (64% identical), U3 (63% identical), SNORD3H (62% identical), U3 (62% identical), U3 (61% identical), and 12 more.